TMED6 (transmembrane p24 trafficking protein 6)
Synonyms: p24gamma5; MGC23911; p24g5; PRO34237; SPLL9146
Tractability: Antibody: UniProt predicts a signal peptide or a membrane-spanning region.
Gene: Protein-coding gene on chromosome 16 (69,343,250 to 69,351,786, reverse strand). Ensembl gene ENSG00000157315.
Subcellular location: Endoplasmic reticulum membrane
Gene Ontology:
Biological process: endoplasmic reticulum to Golgi vesicle-mediated transport; Golgi organization
Cellular component: endoplasmic reticulum-Golgi intermediate compartment; endoplasmic reticulum membrane
Genetic constraint (gnomAD): Loss-of-function variants: 17 observed, 27.82 expected, observed/expected ratio (o/e) 0.61, 90% interval 0.42 to 0.92. The upper end of that interval is the gene's LOEUF score, 0.92, which puts it in group 3 of 6, group 1 being the genes least tolerant of losing a copy. Missense variants: 309 observed, 311.68 expected, observed/expected ratio (o/e) 0.99, 90% interval 0.9 to 1.09. Synonymous variants: 107 observed, 112.87 expected, observed/expected ratio (o/e) 0.95, 90% interval 0.81 to 1.11.
Homologues: Orthologues: chimpanzee TMED6 (99% identical), macaque TMED6 (97% identical), dog TMED6 (92% identical), pig TMED6 (91% identical), rabbit TMED6 (83% identical), rat Tmed6 (78% identical), mouse Tmed6 (78% identical), guinea pig TMED6 (75% identical), tropical clawed frog tmed6 (59% identical), zebrafish tmed6 (42% identical), Drosophila melanogaster loj (21% identical), Caenorhabditis elegans tmed-12 (14% identical). Paralogues in human: TMED4 (21% identical), TMED1 (20% identical), TMED5 (20% identical), TMED9 (20% identical), TMED7 (19% identical), TMED2 (18% identical), TMED3 (16% identical), TMED10 (14% identical).
Diseases named in the same sentence as TMED6 in open-access papers:
TMED6 is named in the same sentence as 5 diseases in open-access papers, as found by Europe PMC text mining. Sharing a sentence is not in itself a finding about the gene and the disease. The quoted sentences say what the papers report.
gastric cancer (2 papers, 2011 to 2012). A primary or metastatic malignant neoplasm involving the stomach. "TMED6, transmembrane emp24 protein transport domain containing 6, has been found to be differentially expressed in different grades of gastric cancer, but no direct evidence has been found to implicate its role in cancer." (PMID 23320390, 2012).
type 2 diabetes (1 paper, 2025). "To date, there have been no reports of an association between TMED6 and either LTL or CVDs, hinting at a potential biological mechanism that may be mediated through CVD risk factors, particularly type 2 diabetes." (PMID 41027922, 2025).
cancer (2 papers, 2011 to 2012). A tumor composed of atypical neoplastic, often pleomorphic cells that invade other tissues. "A few genes were found to be in both the cancer grading and staging signatures, such as CPS1, DES, GFRA3, TMED6 and DPT, indicating some biological relevance between cancer differentiation and progression." (PMID 21445269, 2011).
tumor (1 paper, 2024). "Overall, 8 genes were identified as differentially expressed genes (DEGs) between GC tumor and nontumor tissues (eTable 9 in Supplement 1), with upregulated CDH3 and BAIAP2L2 and downregulated TMED6 also observed in advanced vs mild gastric lesions (eTable 11 in Supplement 1)." (PMID 38809553, 2024).
TMED6 also shares sentences with these, for which no sentence is quoted: diabetes mellitus (1 paper).